CD4 (CD4 molecule)
Diseases named in the same sentence as CD4 in open-access papers (continued):
Sharing a sentence is not in itself a finding about the gene and the disease.
cancer (continued). "Activated neutrophils release neutrophil extracellular traps that exacerbate inflammation in CLD, promoting the onset of HCC, and also facilitate naive CD4+ T cells metabolic reprogramming, correlating positively with regulatory T cell numbers in cancer." (PMID 38730572, 2024). "Of late, in addition to playing an adjuvant role of as helper immune cells in promoting cytotoxic CD8+T lymphocytes as well as the innate immune response, the cytotoxic role of CD4+T cells in cancer has drawn increasing attention." (PMID 39000005, 2024). "DCs present cancer antigens to CD4 + T cells via MHC class II and to CD8 + T cells via MHC class I via costimulatory molecules and positive signals such as TCR, CD28, CD80/CD86, CD40, CD40L, OX40, OX40L, IL12, IFN-α, IFN-α and others." (PMID 39720956, 2024). "We also observe the spatial distribution of CD4+ T cells and CD8+ T cells within the pre-cancer microenvironment, where higher number of CD4+ T cells tend to localize in the stromal compartment within the FAP mucosa." (PMID 39605357, 2024). "For CD4+ T cells, positive correlations were observed in five cancer types: OC (r = 0.164, p < 0.001), GBM (r = 0.140, p < 0.05), KIRP (r = 0.194, p < 0.05), KIRC (r = 0.287, p < 0.001), and KICH (r = 0.287, p < 0.001)." (PMID 39063239, 2024). "Among the 38 scrutinized subsets of immune cells, we observed a direct correlation between FANCD2 expression and the degree of Th2 CD4 + T-cell infiltration across 32 diverse cancer types." (PMID 38443946, 2024). "This study highlights the increased cancer risk in CVID patients, with immune dysregulation, prior immunosuppressant use, elevated IgM levels, and lower CD4 cell counts as conjointly associated." (PMID 39478863, 2024). "Based on these data, we assessed that in carcinoma tissue, more than 70% of the potential IL-17 producers were CD4 helper T cells." (PMID 39454432, 2024). "The expression levels of immunosuppressive markers in CD4+ T cells from cancer mucosa increased with increasing cancer stage." (PMID 37153541, 2023). "The infiltration rate of CD4-Treg cells was significantly higher in cancer tissues than in para-cancerous tissues, especially in GSRC." (PMID 37225691, 2023). "It has been indicated that CD4+ T cells play a central role in orchestrating the host immune response against cancer in animal models." (PMID 37405518, 2023). "Meanwhile, based on the selected CD4+T cells-related hub genes, we constructed a prognostic index for all cancer samples." (PMID 37274740, 2023). "The results revealed that CYFIP2 expression was positively correlated with B cells, CD8 + T cells, CD4 + T cells, macrophages, neutrophils, and dendritic cells in most cancer types based on all or most algorithms, especially in LUAD." (PMID 37735711, 2023). "Significantly, TIM-3 expression on CD4 + T cells correlates with nodal metastasis and advanced cancer stage." (PMID 37567938, 2023). "Most cancer entities exhibited significantly positive Pearson correlations coefficients, with the highest coefficients for CD4, CD8A, and CTLA4." (PMID 36672341, 2023). "Of the 3763 individuals with a cancer during follow-up, 94% had a CD4 measurement within 1 year prior to the diagnosis (median [IQR] time from CD4 measurement to cancer diagnosis 50 days)." (PMID 37509301, 2023). "VIP is also known to exert paracrine effects in cancer by supporting the immunosuppressive activity of CD4+CD25+ regulatory T cells and tolerogenic dendritic cells." (PMID 37444395, 2023). "Although CD4+CD26high T cells are considered for adoptive cancer immunotherapy, the role of CD8+CD26+ T cells is ill-defined." (PMID 36707896, 2023). "Next, the quantified tissue enrichment analysis indicated that the CD4 Tex1 and CD4 Tex2 clusters were mainly enriched in all eight types of cancer." (PMID 37313656, 2023). "Regulatory T-cells (Tregs) play a vital role in disturbing immune environments in cancer patients and are widely defined as FoxP3 + CD4 + T-cells." (PMID 37884996, 2023).
cancer (continued). "Some characteristics concerning the immunosuppressive status (CD4 counts in the LT group) or long-term follow-up in some groups (M6 after the third dose for cancer and LT patients) were also missing." (PMID 37631852, 2023). "In melanoma cells resistant to FAS-induced apoptosis, the death receptor TRAIL facilitated CD4 T cell-induced cancer cell death." (PMID 37654482, 2023). "As expected, the expression of TNFR2 by CD4+FoxP3+ Tregs was much higher than that expressed by conventional CD4 T cells in human cancers." (PMID 36865537, 2023). "TNFα mediates TNFR1-dependent IL-17 production by CD4+ T cells and can promote the activities of immune and cancer cells within tumors." (PMID 36835413, 2023). "CD8+ T cells can directly kill cancer cells, while CD4+ T cells function to regulate other immune cells." (PMID 37532731, 2023). "We found that patients with weak CD4+ cell infiltration and severe CD20+ cell infiltration belong to the group with a low risk of recurrence and the cancer in this group rarely occurs after 10 months (p = 0.0005)." (PMID 38067231, 2023). "Consistently, we found cancer-associated fibroblasts (CAFs), endothelial cells (ECs), and most immune cells, such as CD8+ T cells, CD4+ T cells, and antigen-presenting cells, accounted for different proportions of these 5 clusters." (PMID 36817452, 2023). "In almost all cancers, the T cell CD4+ TH2, the common lymphoid progenitor, and the T cell follicular helper were found to be significantly positively correlated with KIFscores." (PMID 37711200, 2023). "This review will provide an overview of cytotoxic CD4 T cell development, and discuss the role of inflammatory and Tr1-like cytotoxic CD4 T cells in maintenance of intestinal stem cells and in anti-cancer immune responses." (PMID 37654482, 2023). "We observed lower levels of CD4+T, memory CD4+T, and CD4+CD28+T cells in distant metastatic UGI cancers than in locally advanced cancers." (PMID 37346066, 2023). "As per the findings, the low-risk category had remarkably higher levels in most immune cells, including naive CD4 T cells, CD8 T cells, DCs, Cancer associated fibroblast, NK cell, B cell and Monocyte." (PMID 37359528, 2023). "The findings of extensive clinical studies have revealed that immune infiltration, such as CD8+ cytotoxic T-lymphocytes, Th1 and Th17 CD4+ T-cells, and M1 macrophages possess autonomous prognostic value in various cancer types." (PMID 38023241, 2023). "Together, targeting cancer CD39 can correct the mal-differentiation of CD4+ T cells in human NSCLC, providing in-depth insight into therapeutic CD39 inhibitors." (PMID 38062068, 2023). "It was shown that RNF43 expression was significantly associated with various types of infiltrating immune-associated cells including dendritic cells, CD4+ T cells, CD8+ T cells, plasma cells, macrophages, B cells, and so on in diverse cancers." (PMID 37848933, 2023). "The activities of the cancer immunity cycle also confirmed that T-cell recruitment and CD4+ T-cell recruitment from step 4 were upregulated in the high RECK expression group, as well as infiltration of immune cells into tumors." (PMID 37904179, 2023). "For example, CD8 + T-cells, Tregs and CD4 memory resting/activated cells showed an increased abundance in PMLs and cancer." (PMID 37542347, 2023). "This suggests that the proportion of CD4+ cells rose, which would imply that these cells have an important role in cancer escape from the immune system." (PMID 36627701, 2023). "Th1 Cytotoxic CD4+ T cells can directly kill cancer cells in an MHC II-restricted fashion through the secretion of granzyme B and perforin." (PMID 36875137, 2023). "Deficient CD4+ T cells repress the response of cytotoxic T lymphocytes (CTLs), while abundant CD4+ T cells can improve outcomes of cancer immunotherapy strategies." (PMID 38136305, 2023). "Regulatory T cells represent only a minor subset of CD4+ T cells and appear to play an important role in cancer immunology." (PMID 37251931, 2023).
cancer (continued). "Compared with KIRC cohorts with decreased immune cells, the high STON1 group enriched with the anti-cancer immune cells B cells, CD4 + T cells, CD8 + T cells, and macrophages demonstrated a favorable prognosis." (PMID 36759775, 2023). "Accordingly, increasing TAA-specific CD4+ T cells, for example, by vaccination or adoptive cell-transfer has been thought to be crucial to eradicate cancer." (PMID 36939853, 2023). "CD4+ T helper cells play an important role in cancer inhibition and destruction, while regulatory T cells have been shown to promote cancer." (PMID 37445860, 2023). "Our results suggest that immunosuppression in cancer mucosa increases with increasing cell number and increasing proportions of immunosuppressive marker-positive CD4+ and CD8+ cells, respectively." (PMID 37153541, 2023). "High levels of circulating PD-L1 and PD-1 expressed on peripheral CD4+ T cells were detected in patients with cancer, as previously reported." (PMID 37266424, 2023). "The infiltration rate of CD4-Treg cells in cancer tissues was significantly higher than that in para-cancerous tissues, especially in GSRC." (PMID 37225691, 2023). "In this study, we found that the consumption of extracellular methionine by cancer cells induced T cell exhaustion by upregulating PD-1 expression in CD4 T cells." (PMID 37147330, 2023). "CD4 Th2, CD4 Treg, and macrophage M2 are known to be representative immunosuppressive cells that promote cancer growth; hence, we further studied these cells." (PMID 36979179, 2023). "Characteristics of cancer patients vaccinated against SARS-CoV-2 according to high or low levels of CD4 and CD8 senescent immune phenotype (SIP) T-cells." (PMID 37334387, 2023). "As suggested by previous results, the risk score was mostly negatively correlated with the steps of the cancer immunity cycle, including CD4 + T cell, CD8 + T cell, and B-cell recruitment." (PMID 37637055, 2023). "CD4+ T helpers play an important role in cancer inhibition and destruction, while regulatory T cells have been shown to promote cancer." (PMID 37445860, 2023). "This CD8+/CD4+ TSTR group was found to be predictive of an unfavorable response to ICB across multiple cancer types, providing a new T-cell biomarker different from T-cell exhaustion." (PMID 38066642, 2023). "Using TISIDB analysis, our findings revealed that CHST12 mRNA was remarkably negatively correlated with CD4 and Type2 T-helper (Th2) cells, the infiltration of which was critical for immunotherapy producing anti-cancer immunity." (PMID 38333724, 2023). "The genetic ablation of SLC43A2 in cancer cells restores methionine metabolism in CD4 T cells, increasing the intracellular levels of S-adenosylmethionine and yielding H3K79me2." (PMID 37147330, 2023). "According to reports, CD4 T cells inhibit cancer cell proliferation by hindering cell cycle progression at G1/S." (PMID 37733242, 2023). "Clinical and preclinical studies have revealed that intratumoral CD4+ T cells possess cytotoxic capabilities and were capable of directly killing cancer cells." (PMID 37063862, 2023). "Within the cancer context, multiple lines of evidence pointed to an important role for CD4+ T cells in immune responses to cancer immunotherapy." (PMID 37063862, 2023). "Kynurenines have been reported in the cancer literature to support immune escape of tumors via engagement of the PD-1/PD-L1 immune checkpoint and differentiation of CD4+ T cells into immunosuppressive Tregs." (PMID 36422996, 2023). "In contrast, closer proximity between CD133+ cancer stem cells (CSCs), longer distances between CD4+ T cells and CD20+ B cells, CD4+ T cells and neutrophils, and CD20+ B cells and neutrophils were correlated with dismal DFS." (PMID 36588094, 2023). "Within T cells, CD8+ T cells are the primary effector cells to kill cancer cells, and CD4+ T cells, including Tregs and helper T cells, modulate the function of CD8+ T cells." (PMID 38066642, 2023).
cancer (continued). "IL-2 is a pleiotropic cytokine mainly produced by antigen-stimulated CD4+T lymphocytes, which has as an important role in promoting a cellular immune response against intracellular microorganisms and cancer cells." (PMID 36984496, 2023). "Among which, IL18RAP was associated with activated CD4+ memory T cells in 24 cancer types, CD8+ T cells in 24 cancer types, and M1 macrophages in 27 cancer types in a positive correlation." (PMID 37698530, 2023). "In a prior study, IL-17 triggered the PD-1 pathway in cancer cells creating an immunosuppressive microenvironment dominated by Treg cells whereas CD4 and Cd8 cells were inhibited." (PMID 37719029, 2023). "CDK4/6 inhibitors induce their anti-cancer activity through the CD4/6-Rb axis, which is often disrupted in the majority of cancers and is at the basis of abnormal cell proliferation." (PMID 37895811, 2023). "Macrophages, CD4+ T cells, cancer HER2_sc, and mature luminal cell types were significantly enriched in TNAC compared to LK-TNBC (Wilcoxon signed-rank test, p < 0.05)." (PMID 37394589, 2023). "The differentiation of CD4+ cells into an immunosuppressive Treg subset is a crucial pathway of cancer immune evasion." (PMID 37711611, 2023). "CD8+ T cells, CD45RO+ (CD4+ T memory cells) and NK cells were slightly more abundant in patients and cancer types with longer overall survival." (PMID 36649303, 2023). "Specifically, we compared T cell PD-L1/PD-1 expressions in cancer lesions between wildtype mice and knockin mice and CD4+/− and CD8+/− T cell expression." (PMID 37298359, 2023). "The CD4+ T cell has been wildly demonstrated to possess cytotoxic programs and can directly kill cancer cells." (PMID 36998462, 2023). "After adjusting for purity, infiltration of representative immune cells including Tregs, CD4+ T cells, and CD8+ T cells, along with cancer associated fibroblast, was measured." (PMID 39282155, 2023). "Cytotoxic CD4 T cells have been shown to have features of different helper T cell subsets - this has also been seen in cancer patients." (PMID 37654482, 2023). "Plasma EVs from HCC patients exhibit immunological, cancer, and coagulation markers, including potential biomarkers (CD4, CD20, CD49e, CD146)." (PMID 37569887, 2023). "IL-10 can also inhibits CD4+ T cell proliferation and suppresses activation of immune effector cells such as T cells to assist cancer cell escape from immune surveillance." (PMID 37612278, 2023). "In particular, the adoptive transfer of TCR gene-engineered T cells (TCR-T) would be a promising strategy for increasing TAA-specific CD4+ T cells in cancer patients." (PMID 36939853, 2023). "On the contrary, the high-DR score group displayed lower levels in Step 3 (priming and activation), Step 4 (CD4 T cell recruiting), Step 5 (infiltration of immune cells into tumors), and Step 7 (killing of cancer cells) compared to the low-DR score group." (PMID 38132439, 2023). "IL-2 administration has been shown to increase CD4+CD25+Foxp3+ Treg numbers in patients with cancer." (PMID 38004268, 2023). "Circulating CD4+ helper T cell (Th) subsets provide potentially important information on disease progression in several cancers." (PMID 36925914, 2023). "Lack of methionine and S-adenosylmethionine due to the high consumption by cancer cells leads to CD4 and CD8 T cells dysfunction and exhaustion, inhibition of Th17 proliferation, and cytokine production." (PMID 37568713, 2023). "We found that the apoptosis of human peripheral PD-1+CD4+ T cells was significantly elevated in patients with cancer compared with healthy donors and was positively correlated with circulating PD-L1 levels in patients with cancer." (PMID 37266424, 2023). "Generally, BCG is internalized primarily by cancer cells leading to cytokine production and the activation of CD4+ and CD8+ T-cells, leading to the killing of cancer cells." (PMID 37727793, 2023).
cancer (continued). "We here identify the transcriptomic imprint of DC licensing by CD4+ T-cells in human cancer and pinpoint the cDC1 as the recipient of CD4+ T-cell help in the human TME." (PMID 36639382, 2023). "Both isoforms have previously been shown to induce differentiation of CD4+ T cells to Treg phenotypes, and their relative expression varies in some autoimmune diseases, inflammatory diseases, and cancers." (PMID 37868998, 2023). "CX3CL1 expression was positively correlated with the infiltration levels of CD4+ T cells, M1 macrophage cells, and activated mast cells in various cancers." (PMID 37153002, 2023). "Studies about chronic viral infection and cancer have shown that CD4 T cells are necessary for CD8 T cell function, CD4+ T cells are dispensable for primary expansion and cytotoxic effectors of CD8+ T cells." (PMID 38082437, 2023). "This study demonstrates the biological importance of prioritizing and including CD4+ T cell–specific neoantigens for personalized cancer vaccine modalities." (PMID 38063199, 2023). "Later, they illustrated that HLA class II genotypes, under the surveillance of CD4+ T cells, are also important for immunoediting in early cancer development." (PMID 37942321, 2023). "RRS1 was related to B cells in 13 cancers, CD4+ T cells in 14 cancers, CD8+ T cells in 15 cancers, myeloid dendritic cells in 17 cancers, macrophages in 16 cancers, and neutrophils in 13 cancers according to TIMER analysis." (PMID 37090698, 2023). "The outstanding associations between C-to-U RESs across different cancer types and different ICCs were also impressive, for example, CAVIN1 RESs with CD4+ T cells or M2 macrophages, and VWA8 with M1 or M2 macrophages." (PMID 36969056, 2023). "Here, the enhanced consumption of methionine by cancer cells facilitated the suppression of CD4 T cells by reducing AMPK expression." (PMID 37147330, 2023). "One of the many ways that a B-cell activity can stop the formation of cancers is through stimulating CD4+ T cells and CD8+ T cells, as well as by producing antibodies that are reactive to tumors." (PMID 36733434, 2023). "According to our manual analysis and what has been reported in patients with chronic infections and different types of cancer, we found increased CD4 (Pop 18 and Pop19) and CD8 (Pop5 and Pop10) exhausted clusters in BC samples." (PMID 36763585, 2023). "The ability of CD4+ T cells to augment CD8+ T-cell antitumor responses is supported by data from a WT1-based therapeutic cancer vaccine containing only HLA-II antigens." (PMID 36138335, 2023). "In a following study, patients with different cancers were treated with autologous CD4+ T cells purified from peripheral blood and engineered to express a TCR specific for the shared MHC Class II-restricted tumor antigen MAGE3." (PMID 37965314, 2023). "Previous reports indicated that T Cell CD8 and T Cell CD4 function affected clinical outcomes in cancer patients." (PMID 37596597, 2023). "Upon analyzing the TILs, we observed a lower CD4/CD8 ratio in aging mice, which can be associated with immunosenescence as well as poorer disease outcome for certain cancers." (PMID 37752597, 2023). "Vaccination using FeMOF-based cancer vaccines efficiently increase the cell populations of typical T lymphocytes in immune organs, such as CD4+, CD8+ cells and so on." (PMID 38259474, 2023). "We found that levels of CD8+ T cells or CD4 memory activated T cells were higher in EGFR wild-type and rare variant cancers than in EGFR L858R and exon 19 deletion types." (PMID 37033978, 2023). "The naive mice were not exposed to any foreign antigens, either from Salmonella or cancer cells, and therefore showed only a basal level of CD4+ and CD8+ cells." (PMID 37941832, 2023). "An efficient cancer vaccine should ideally be able to reinforce the body’s natural defenses against cancer by eliciting potent CD4+ and CD8+ T effector and memory response." (PMID 37513965, 2023).